HSPB1 (heat shock protein family B (small) member 1)
Diseases named in the same sentence as HSPB1 in open-access papers (continued):
Sharing a sentence is not in itself a finding about the gene and the disease.
celiac disease (1 paper, 2015). An autoimmune genetic disorder with an unknown pattern of inheritance that primarily affects the digestive tract. "Seven genes were down-regulated in the biopsies of celiac disease patients, among them NTS down-regulated 3.6 fold and the INSR, APPL2, ADCY9, GLS, HSPB1 and KIF13A 1.5-2.2 fold in the patient group (p < 0.001)." (PMID 26123480, 2015).
cerebellar degeneration (1 paper, 2016). Degeneration of the cerebellum. "Our findings suggest that strategies that promote HSPB1 expression or phosphorylation may diminish the rate of cerebellar degeneration in NPC disease." (PMID 27152617, 2016).
chronic heart failure (1 paper, 2024). "HSPB1 is an independent predictor of prognosis in patients with chronic heart failure, and its activation can also improve myocardial fiber arrangement and restore cardiac diastolic function." (PMID 39711549, 2024).
Clear Cell Renal Cell Carcinoma (1 paper, 2022). "In this study, we discovered a novel endogenous peptide derived from HSPB1 protein through peptidomic analysis of human renal clear cell carcinoma and adjacent normal tissues." (PMID 36428802, 2022).
Cognitive impairment (1 paper, 2023). Abnormal cognition is characterized by deficits in thinking, reasoning, or remembering. "Some studies have found that EA at GV24 and GV20 can affect the proteomics changes of hippocampus in rats with cognitive impairment, and the up regulation of DAMPs such as heat-shock protein β1 (Hspb1) may participate in the molecular mechanism of EA to improve cognitive impairment." (PMID 37397457, 2023).
contact dermatitis (1 paper, 2019). An inflammatory skin condition caused by direct contact between the skin and either an irritating substance or an allergen. "Also parabens, a class of preserving additives found in cosmetics that can cause skin irritation and contact dermatitis, elevated the levels of HSPB1 in skin equivalents." (PMID 31734893, 2019). "Proteomic analysis revealed that HSPB1 is among several proteins upregulated in human epidermis, or primary foreskin keratinocytes exposed to sodium lauryl sulfate (SLS), a surfactant widely used for inducing the experimental contact dermatitis." (PMID 31734893, 2019).
Crohn disease (1 paper, 2025). A gastrointestinal disorder characterized by chronic inflammation involving all layers of the intestinal wall, noncaseating granulomas affecting the intestinal wall and regional lymph nodes, and transmural fibrosis. "Additionally, HSPB1 exerts a role in Crohn’s disease by mediating TNF-α-stimulated myofibroblast migration and contributes to renal tubulointerstitial fibrosis by modulating E-cadherin expression through Snail downregulation." (PMID 39863585, 2025).
distal hereditary motor neuropathy type 2B (1 paper, 2018). "Mutations in small heat shock protein beta‐1 (HspB1) have been linked to Charcot‐Marie‐Tooth (CMT) disease type 2F and distal hereditary motor neuropathy type 2B." (PMID 29381233, 2018).
experimental autoimmune encephalomyelitis (1 paper, 2024). An autoimmune demyelinating disease of the central nervous system that is produced experimentally in animals by the injection of homogenized brain or spinal cord in Freund's adjuvant. "Treatment with recombinant HSPB1 has shown translational potential, reducing the paralytic symptoms when injected intraperitoneally in the experimental autoimmune encephalomyelitis mouse model, alongside decreased levels of the inflammatory cytokines IL-2, IL-6, and IFNγ." (PMID 38507480, 2024).
filaminopathy (1 paper, 2020). "In accordance, in the muscle fibers of MFM-filaminopathy patients, HSPB1 and HSPB5 are strongly upregulated, translocated away from Z-discs and highly concentrated in pathologic aggregates." (PMID 32887649, 2020).
head and neck cancer (1 paper, 2012). A primary or metastatic malignant neoplasm affecting the head and neck. "Our findings of a decrease in HSPB1 mRNA expression associated with a more aggressive PCa phenotype is in contrast to studies of protein level expression of HSPB1 in PCa and breast, ovarian and head and neck cancer." (PMID 22075945, 2012).
hearing loss (1 paper, 2014). "A limitation of the present study is that we cannot be sure about the importance of the up-regulation of Hspb1 expression in old age with severe hearing loss." (PMID 24587312, 2014). "These three genes were: Hspb1 (p = *0.0345, F = 3.79, df = 2,29) and Gpx6 (p = **0.0011, F = 8.644, df = 2,29) that showed significant up-regulation and Txnrd1 (p = 0.6575, F = 0.4254, df = 2,29) that showed down-regulation with age and hearing loss." (PMID 24587312, 2014). "Hspb1 changes showed upregulation only in the old severe hearing loss group that may indicate its main relation with hearing loss." (PMID 24587312, 2014).
hepatitis B infection (1 paper, 2024). "Moreover, HSPB1 has also been found to exert an anti-viral effect through downstream anti-viral effector proteins during hepatitis B infection." (PMID 39071496, 2024).
hepatoblastoma (1 paper, 2024). Hepatoblastoma (HB) is a malignant hepatic tumor and is the most common pediatric liver cancer. "A study has highlighted that the O-GlcNAcylation modification of HSPB1 promotes proliferation and enhances the chemotherapeutic resistance of hepatoblastoma cell lines in vitro experiments." (PMID 38390281, 2024).
Huntington disease (1 paper, 2022). Huntington disease (HD) is a rare neurodegenerative disorder of the central nervous system characterized by unwanted choreatic movements, behavioral and psychiatric disturbances and dementia. "Overexpression of the human HspB1 helps decrease protein aggregation in mouse models of Huntington’s disease, although the mechanism is not well understood." (PMID 34610126, 2022).
Hypercholesterolemia (1 paper, 2025). An increased concentration of cholesterol in the blood. "The decreased serum LDL concentration in the APOB/HSP males suggests a direct protective effect of human HSPB1 overexpression against hypercholesterolemia." (PMID 40855499, 2025). "In addition, here we demonstrated that human HSPB1 overexpression also shows sex-dependent effects on weight gain, hypercholesterolemia, and hepatic and vWAT gene expression." (PMID 40855499, 2025).
Hyperreflexia (1 paper, 2017). Hyperreflexia is the presence of hyperactive stretch reflexes of the muscles. "Hyperreflexia, observed in this T139M phenotype, serves as a feature for appreciating the microscopic anatomy of the disease process resulting from HSPB1 mutations." (PMID 28828227, 2017).
Hyperthermia (1 paper, 2016). "Hyperthermia and Hspb1 are both involved in the regulation of apoptosis and necrosis." (PMID 27626679, 2016).
Hypoglycemia (1 paper, 2021). A decreased concentration of glucose in the blood. "In control subjects, HSPB1, SMAD3 and HSPA1A decreased significantly, whilst MAPKAPK5 increased significantly in controls from baseline to hypoglycemia whilst, in T2D, PPP3CA increased and EPHA2 decreased." (PMID 34426634, 2021).
injury (1 paper, 2021). Damage inflicted on the body as the direct or indirect result of an external force, with or without disruption of structural continuity. "In order to shed light on the exact mechanism of inflammation modulation by HSPB1, we investigated the effect of HSPB1 on neuroinflammatory processes in an in vivo and in vitro model of acute brain injury." (PMID 33423680, 2021).
insulinoma (1 paper, 2021). "Like HSPB1, exendin-4 was reported to alleviate ER stress induced by exposure of rat insulinoma cells to high glucose and palmitate." (PMID 34571827, 2021).
Intellectual disability (1 paper, 2025). "Clinical clues to pinpoint the causative gene from the heterogeneous CMT2 and AR‐CMT2 group included pyramidal signs in SACS, MTRFR, and HSPB1, vocal cord paralysis in TRPV4, intellectual disability in MCM3AP, late disease onset in MME, in accordance with previous reports." (PMID 39776111, 2025).
jejunal cancer (1 paper, 2022). A malignant neoplasm involving the jejunum. "We found that some upregulated DEGs in GC malignant cells such as HSPB1, PHLDA2, DNAJB1 have the decreasing expression tendency in malignant cells from GC, duodenal caners, jejunal cancers to CRC." (PMID 36104333, 2022).
liver cirrhosis (1 paper, 2024). "Conversely, high HSPB1 expressions have also been found to be associated with liver injury; its expressions were elevated in patients with liver cirrhosis, where knocking down HSPB1 alleviated fibrosis." (PMID 39071496, 2024).
liver diseases (1 paper, 2024). "Furthermore, the HSPB1 gene plays a role in the onset and progression of numerous liver diseases." (PMID 38809509, 2024).
MELAS (1 paper, 2022). "On the contrary, the expression of HSPB1, CRYAB and S100A9 were significantly up-regulated in MELAS patients." (PMID 36254078, 2022).
meningioma (1 paper, 2017). A generally slow growing tumor attached to the dura mater. "Overexpression of HSPB1 was found to be associated with poor prognosis for patients with meningioma." (PMID 28903393, 2017).
metastatic cancer (1 paper, 2014). A carcinoma which has spread from the original site of growth to another anatomic site. "Also, it has been reported that O-GlcNAcylation of HSPB1 was detectable in metastatic cancer." (PMID 24465581, 2014).
metastatic melanoma (1 paper, 2012). A melanoma that has spread from its primary site to another anatomic site. "Furthermore, we investigated the differential expression of genes HSPB1, SERPINE1 and FBLIM1 in a panel of five patient-derived metastatic melanoma cell lines in comparison to FM305 primary melanocytes." (PMID 22984562, 2012).
metastatic prostate carcinoma (1 paper, 2023). A carcinoma that arises from the prostate gland and has spread to other anatomic sites. "Similar to our results, previous studies had shown that HSPB1 acted as a biomarker for survival prediction in late metastatic prostate cancer." (PMID 37010714, 2023).
morphine dependence (1 paper, 2014). Strong dependence, both physiological and emotional, upon morphine. "Among these DEGs, Lcn2 and Hspb1 participated in the regulation of NF-κB pathway activation, which plays a complex role in morphine dependence." (PMID 25012590, 2014).
myocarditis (1 paper, 2011). Myocarditis is a condition that is characterized by inflammation of the heart muscle (myocardium). "Strikingly, of the 39 up-regulated proteins identified in this experiment, UPR target genes, such as GRP78, GRP94, Hspb1, Calr, and Pdia3, were also increased in the acute phase of CVB3-infected myocarditis mouse heart tissues." (PMID 22014063, 2011).
myopia (1 paper, 2017). "Such expression changes were evident, particularly in the late myopia dataset where a wide range of genes linked with oxidative stress were either up-regulated (GPX1, GSTA3, MT-4, APOA1, OTUB, PTGDS, HSPB1, HSPB2) or down-regulated (XHD, SLC40A1, TF, SOD3, HPGDS, BCMO1)." (PMID 28852117, 2017).
myxoma (1 paper, 2024). A benign soft tissue neoplasm characterized by the presence of spindle and stellate cells, lobulated growth pattern, and myxoid stroma formation. "Macrophages in myxoma were associated with the upregulation of NFKB1, PDGFC, and IL1B, as well as the downregulation of ATP5PB, HSPB1, and IFI27." (PMID 39090109, 2024).
oesophagitis (1 paper, 2021). "So far, only the SNP in the HSPB1 gene has been reassessed in association with oesophagitis and pneumonitis." (PMID 33810047, 2021). "We found the SNP rs2868371 in HSPB1 associated with oesophagitis CTCAE grade of ≥2 at the 15-week follow-up (HR = 3.72; 95% CI = 1.49–9.25; unadjusted p-value = 0.004; adjusted p-value = 0.083)." (PMID 33810047, 2021).
osteoporosis (1 paper, 2023). A condition of reduced bone mass, with decreased cortical thickness and a decrease in the number and size of the trabeculae of cancellous bone (but normal chemical composition), resulting in increased fracture incidence. "Phosphorylated HSPB1 was involved in the pathogenesis of osteoporosis." (PMID 37231424, 2023).
Pancytopenia (1 paper, 2023). An abnormal reduction in numbers of all blood cell types (red blood cells, white blood cells, and platelets). "Bioinformatic analysis showed that HSPB1 was highly expressed in pancytopenia and was associated with poor prognosis." (PMID 37241117, 2023).
Parkinson’s disease with dementia (1 paper, 2025). "Another study reports the HspB1 overexpression in reactive astrocytes in Parkinson’s disease with dementia (PDD)." (PMID 40003991, 2025). "HspB5, along with HspB1, was reported to be overexpressed in reactive astrocytes in Parkinson’s disease with dementia (PDD), with HspB5 expression also limited to microglia cells." (PMID 40003991, 2025).
periodontal disease (1 paper, 2015). "In a previous study we aimed to compare the interproximal pocket tissue with interproximal tissues at sites with normal probing depth in patients affected from periodontal disease and HSPB1, LEG7 and 14-3-3 proteins resulted significantly under-expressed." (PMID 26719749, 2015).
peripheral motor neuropathies (1 paper, 2022). "This is especially evident if HspB1, HspB3, and HspB8 are compared, all of them causing, when mutated, a similar spectrum of peripheral motor neuropathies." (PMID 35678958, 2022).
pheochromocytoma (1 paper, 2021). "HSPB1 has been reported to participate in the degradation process of the proapoptotic factor BIM, promoting greater survival of pheochromocytoma-derived PC12 tumor cells subjected to ER stress." (PMID 34571827, 2021).
pituitary adenomas (1 paper, 2023). "The objective of this study is to investigate the expression profile and prognostic value of HSPB1 (heat shock protein beta-1) in pituitary adenomas with invasive and non-invasive features." (PMID 37241117, 2023). "Our analysis of transcriptome sequencing results in 159 pituitary adenomas revealed that the HSPB1 gene was significantly highly expressed in invasive pituitary adenomas." (PMID 37241117, 2023). "In our study, we screened for HSPB1 by analysing transcriptome sequencing data, a key gene in invasive pituitary adenomas, and performed adequate bioinformatics analysis." (PMID 37241117, 2023). "In conclusion, our study showed that HSPB1 expression is upregulated in invasive pituitary adenomas and affects immune cell infiltration." (PMID 37241117, 2023). "Inhibitors of HSPB1 expression are currently available, making it a potential target for therapy in invasive pituitary adenoma." (PMID 37241117, 2023). "The data showed that high expression of HSPB1 was negatively correlated with T-cell infiltration in 159 pituitary adenoma samples, which may predict an immunosuppressive function of HSPB1." (PMID 37241117, 2023). "Additionally, we aim to explore the potential relationship between HSPB1 expression and immunological functions in pituitary adenoma." (PMID 37241117, 2023). "Therefore, the aim of this study was to explore the expression profile and prognostic value of HSPB1 in pituitary adenoma and investigate the potential relationship between HSPB1 expression and immunological functions." (PMID 37241117, 2023). "It was demonstrated that the HSPB1 gene played an important role in the invasion of the cavernous sinus by pituitary adenomas and that the HSPB1 gene might be a key gene in the invasion of the cavernous sinus by pituitary adenomas." (PMID 37241117, 2023). "HSPB1 may be a potential target for the treatment of invasive pituitary adenoma." (PMID 37241117, 2023). "Although there is increasing evidence that HSPB1 may play a vital role in the tumorigenesis of some specific types of cancers, a systematic analysis of HSPB1 in pituitary adenoma has not yet been conducted." (PMID 37241117, 2023).
pituitary tumor (1 paper, 2023). A benign or malignant neoplasm affecting the pituitary gland. "Recent research has identified HSPB1, which is involved in tumor progression by modulating the immune response, as a potential target in invasive pituitary tumors, as inhibitors of HSPB1 expression are currently available." (PMID 37958702, 2023).
Pleural effusion (1 paper, 2025). The presence of an excessive amount of fluid in the pleural cavity. "We also identified pleural effusion predictive gene signatures, including TMPRSS3, MS4A7, NAPSA, and IGFBP2, while liver metastasis predictive markers included WFDC2, HSPB1, COX6C, APOE, and TUBA1A." (PMID 39955556, 2025).
proliferative diabetic retinopathy (1 paper, 2022). Advanced retinopathy due to diabetes mellitus characterized by the formation of new vessels in the retina. "HspB1 can promote VEGF folding and secretion and thus could promote angiogenesis in proliferative diabetic retinopathy and neovascular AMD." (PMID 35480891, 2022).
retinal ischemia (1 paper, 2022). A ischemic disease that involves the retina. "There is recent evidence from the retinal ischemia rat model that HSPB1 (rather than other common HSPs) is the transcriptional target of the hypoxia-inducible factor (HIF)-1α transcription factor." (PMID 35099007, 2022).
salivary gland tumors (1 paper, 2024). "Some of the identified peptides were derived from proteins previously suggested as potential biomarkers of salivary gland tumors (ANXA1, BPIFA2, FGB, GAPDH, HSPB1, IGHG1, VIM) or tumors of other tissues or organs (SERPINA1, APOA2, CSTB, GSTP1, S100A8, S100A9, TPI1)." (PMID 39201484, 2024).
skin aging (1 paper, 2021). The gradual irreversible changes in structure of skin that occur as a result of the passage of time.. "In the next core pathway of both middle-aged and elderly skin aging, the ligand KITLG promotes melanin synthesis, DNA damage, and inhibits cell-cycle arrest by modulating TFs AR and MITF via signaling transduction proteins FAM83H, HSPB1, PAX3, ATF5, and H2AFB2." (PMID 34073305, 2021).
Spastic paraplegia (1 paper, 2017). Complete loss of the ability to move the lower limbs accompanied by spasticity of the lower limbs. "(2010) reported a 27‐year‐old man from a large family possessing R127W mutation in HSPB1 presented with spastic paraplegia‐like features, where other family members had phenotypes compatible with classification and diagnostic guidelines for CMT2 and dHMN." (PMID 28828227, 2017).
testis tumor (1 paper, 2020). "However, HspB1 was also suggested as a suppressor for cell proliferation in human testis tumor cells." (PMID 32927696, 2020).
triple-negative breast carcinoma (1 paper, 2023). An invasive breast carcinoma which is negative for expression of estrogen receptor (ER), progesterone receptor (PR), and human epidermal growth factor receptor 2 (HER2). "Concordantly, HSPB1 expression was significantly increased in triple-negative breast cancer cells (p < 0.01)." (PMID 37268925, 2023). "We then used RT-PCR to detect the expression of HSPB1 in triple-negative breast cancer cells (MDA-MB-468, MDA-MB-157, and MDA-MB-231) and non-triple-negative breast cancer cells (MCF-7, MDA-MB-453, and BT474)." (PMID 37268925, 2023).